LEP (leptin)
Diseases named in the same sentence as LEP in open-access papers (continued):
Sharing a sentence is not in itself a finding about the gene and the disease.
Obesity (continued). "Another study stated that miR-208, an oncomiR, acts as an obesity trigger in mouse cardiomyocyte cells and its expression decreases in the presence of mTOR inhibitor rapamycin, while weight loss increases despite leptin resistance." (PMID 37529006, 2022). "Still, for those individuals with leptin deficiency, leptin supplementation produced a miraculous reduction in their hunger and obesity." (PMID 35662925, 2022). "In our study, we examined the association of several polymorphisms at the PLIN locus with obesity and lipid profile in children, and then analyzed the mediation of plasma leptin levels on these associations." (PMID 35893926, 2022). "Several polymorphisms of LEP were studied in different populations for their potential association with obesity and metabolic complications." (PMID 36619235, 2022). "They found that the LEP SNPs rs7799039 and rs2167270 were independently and significantly associated with the risk of obesity." (PMID 36293132, 2022). "Adipocytokines including ADPN, resistin, and LEP have been found to be associated with obesity, insulin resistance, β-cell dysfunction, endothelial dysfunction, dyslipidemia, and inflammation." (PMID 35418966, 2022). "The subject with obesity having “A” variant in heterozygous condition had increased serum leptin level with family history of obesity while the control subjects with mutant “A” allele in heterozygous condition had normal serum leptin level." (PMID 36619235, 2022). "Energy adaptations in response to RYGB bariatric surgery in people with severe obesity were associated with changes in insulin, leptin, adiponectin, T3, intestinal hormones, and SNS activity." (PMID 36349055, 2022). "Since there is no uniform, widely accepted definition of “relative leptin deficiency” in patients with obesity, the question arises how to identify patients with relatively low leptin levels." (PMID 35677722, 2022). "Decreased cognitive function is associated with impaired metabolic pathways associated with obesity such as insulin signaling and leptin regulation." (PMID 35509009, 2022). "The main risk factors for COVID-19 mortality, namely age, obesity, type 2 diabetes and impaired renal function, find a common denominator in leptin and insulin resistance." (PMID 35406000, 2022). "The causal relationship between obesity, hyperleptinemia and leptin resistance was demonstrated in laboratory animals." (PMID 35406000, 2022). "Identification of the obesity gene-encoded leptin in 1994 and characterization of its function as a major appetite suppressant are landmarks in obesity, endocrinology, and metabolism research." (PMID 36618698, 2022). "The peptide hormone leptin (Lep), one of the first identified adipocytokines,is encoded by the ob gene (obesity gene)." (PMID 36348712, 2022). "The leptin pathway has been consistently associated with food intake and energy expenditure by various authors and associated with obesity and obesity-related diseases." (PMID 35741707, 2022). "DNA methylation is involved in regulating gene expression, including the leptin gene, which increases the risk of developing obesity." (PMID 36551896, 2022). "Since leptin regulates satiety and food intake and working the nightshift is associated with obesity, one possible explanation for our findings is that the higher levels of leptin reflect an underlying state of leptin resistance." (PMID 35615722, 2022). "Homozygosity for pathogenic variants in the leptin gene leads to congenital leptin deficiency causing severe early-onset obesity." (PMID 36121795, 2022). "Since higher leptin levels correlate with increased cardiovascular risk and inflammation, leptin is suggested to be an important factor linking obesity, MetS, and CVDs." (PMID 35054972, 2022). "Leptin is thought to be responsible for several cardiovascular diseases associated with obesity, while adiponectin is considered to be cardioprotective." (PMID 35990345, 2022).
Obesity (continued). "LEP encodes leptin, a protein that plays an essential role in regulating appetite, energy homeostasis, and obesity." (PMID 35655232, 2022). "Obesity can cause chronic inflammation and increase the level of leptin, activation of protein kinases, activation of polyol pathways, and other mechanisms that can elevate the oxidative stress inside the cell." (PMID 36059323, 2022). "High expression, rare mutations, and single-nucleotide polymorphisms (SNPs) of leptin were found in such obesity classes, delineating an association of leptin genetics, obesity, and CRC." (PMID 35563103, 2022). "Following the first mutation in the LEP gene found in mice, a nonsense C→T mutation in codon 105, ob/ob deficient mice (LEPob/LEPob) became a common model for obesity." (PMID 35563103, 2022). "Particularly, single-gene pathogenic variants in genes belonging to the leptin-melanocortin signaling pathway, which is fundamental to the regulation of energy homeostasis, have been shown to independently cause obesity." (PMID 36292633, 2022). "One of the proposed mechanisms for how sleep loss is a risk factor for obesity is how the hormones related to appetite regulation, leptin and ghrelin, become unbalanced." (PMID 36612601, 2022). "Leptin and adiponectin are factors that are released by adipocytes, and they are highly associated with obesity." (PMID 36232660, 2022). "Obesity is linked to the expression, rare mutations, and polymorphic profiles of LEP and LEPR genes, as well as epigenetic events and other genes involved in energy regulation and metabolism." (PMID 35563103, 2022). "A novel synonymous mutation rs142904532 (Thr5Thr) of exon 2 of LEP locates at chromosome 7 : 128252033 was observed in one subject with obesity." (PMID 36619235, 2022). "In conclusion, our findings suggest that HF-induced obesity symptoms become more severe in maternal protein-restricted offspring, and plasma biomarkers such as leptin and BCAAs strongly reflect an increased risk of obesity." (PMID 35267386, 2022). "Collectively, the study indicated that the obesity-associated hormone leptin plays an indispensable role in promoting the inflammation of allergic airways in asthma by activating lung immune cells and modulating the influx of circulating immune cells." (PMID 35888038, 2022). "Fatty acid-binding protein adipocyte (FABPa) has been associated with lipid metabolism disorders, diabetes and obesity and interacts with leptin (Gan, Liu, Cao, Zhang, & Sun, 2015)." (PMID 35039097, 2022). "Few studies have examined the association between circulating leptin levels and steatosis hepatis in children and adolescents with obesity." (PMID 35677722, 2022). "Obesity, in association with high levels of adipokines (leptin and resistin), was reported to promote earlier development of knee OA in younger patients." (PMID 35270000, 2022). "Obesity has been linked to both hyper- and hypo-methylation of CpG sites across the genome, which in turn associate with the regulation of leptin, adiponectin, and other features of cellular energy balance." (PMID 35585103, 2022). "Various mutations in the LEPR gene leading to leptin signaling deficiency through disruption in the LEPR function resulted in many cases in obesity/diabetes phenotypes in humans and rodents." (PMID 35650533, 2022). "This suggests that under obesogenic conditions, hyperleptinemia is associated with leptin resistance, which further contributes to the development of obesity and associated metabolic disorders." (PMID 35628332, 2022). "Since leptin inhibits AgRP neurons promoting a negative energy balance, resistance to this anorexigenic action of leptin is strongly associated with obesity, IR, and MetS." (PMID 35204276, 2022). "And, studies suggest that there is a positive correlation between circulating leptin levels and greater future BMI or body adiposity, which can predict the risk of future obesity in children, so lowering leptin levels is crucial for obese children." (PMID 35720911, 2022).
Obesity (continued). "Chronic exposure to the elevated leptin levels associated with obesity alter post-receptor signaling in these cells, lowering JAK2 phosphorylation and decreasing production of interferon-γ." (PMID 35752704, 2022). "The genetic variation in FAAH expression is associated with the hypophagic effects of leptin and obesity." (PMID 35565526, 2022). "The leptin-deficient db/db mouse model used in our study has previously been shown to be affected by the metabolic disorders of obesity and T2DM, including elevated blood glucose and abnormal insulin secretion." (PMID 35915136, 2022). "Its pathogenesis is mainly mediated by obesity-associated hyperinsulinemia, increased circulating levels of leptin, resistin, and various cytokines by altering the gut microbial flora and oxidative stress." (PMID 36059323, 2022). "Given that adiponectin and leptin work inversely, a decrease in the adiponectin/leptin ratio reflects alterations in obesity-associated metabolic disturbances." (PMID 36232660, 2022). "In this study, we utilized obese mouse models driven by a high-fat diet, the leptin-deficient ob/ob mouse, and the leptin receptor deficient db/db mouse to determine the effect of obesity in endometriosis development." (PMID 36140261, 2022). "Obesity causes increasing inflammation in the CNS, as well as an increase in circulating serum leptin." (PMID 36313760, 2022). "Morbid early childhood obesity with normal development suggests leptin pathway gene mutation (LEP, LEPR, and PCSK1 mutations), if delayed development consider Prader-Willi syndrome or Bardet-Biedl syndrome." (PMID 35530907, 2022). "One study showed an association between obesity and depression due to the presence of genes contributing to depression, such as genes that encode glucocorticoids, leptin, and dopamine receptors." (PMID 35457752, 2022). "Mice with leptin deficiency (ob/ob) or leptin signaling deficiency (db/db) develop severe obesity due to hyperphagia." (PMID 35909571, 2022). "A novel missense mutation Phe17Leu (LEP rs201067336) was found to be linked with obesity in the study population." (PMID 36619235, 2022). "Leptin-deficient individuals suffer from obesity, and the administration of recombinant leptin has been shown to effectively reduce fat tissue mass." (PMID 35269504, 2022). "More study is needed to investigate the mechanism of CTRP1 in appetite regulation and the causal relation between leptin and obesity after CTRP1 treatment." (PMID 36195912, 2022). "Nevertheless, studies have shown that the deletion of JNK1 and IKKβ in neurons can rescue leptin and insulin signaling in the hypothalamus, as well as reduce weight gain and restore the metabolic alterations linked to obesity." (PMID 35112705, 2022). "This study suggests that the obesity-elevated leptin level is associated with a higher risk of developing CRC in males." (PMID 36429114, 2022). "We initially focused on the hormones insulin, leptin and adiponectin, as these are known to be directly associated with obesity and are often linked to a type 2 diabetes (T2D)-like phenotype." (PMID 35626717, 2022). "Various mutations of LEP have been associated with obesity grade and age of onset, varying across countries, regions, ethnicities, and other factors, while showing inconsistent associations with other obesity-related diseases." (PMID 35563103, 2022). "In contrast to this canonical model, genetically engineered mice are more susceptible to severe obesity, such as leptin-deficient (ob/ob) mice, leptin receptor-deficient (db/db) mice, and carboxypeptidase E-deficient (Cpefat) mice." (PMID 36051916, 2022). "Although rare monogenic variants associated with obesity result from highly infrequent single-gene mutations (such as LEP, POMC), some of them were also associated with polygenic obesity (e.g., MC4R, FTO)." (PMID 35806402, 2022).
Obesity (continued). "Pharmacological induction of ER stress or deletion of XBP1 in neurons result in hyperleptinemia and obesity, associated with severe hypothalamic leptin resistance." (PMID 34523036, 2022). "Leptin deficient mice (ob/ob) and humans or leptin receptor deficient mice (db/db) develop severe obesity." (PMID 36479348, 2022). "Leptin has pleiotropic functions, contributes to obesity-associated chronic low-grade inflammation, and plays an important role in IVDD pathophysiology." (PMID 36293132, 2022). "A recent study suggested the possible association of “NOTCH4-GATA4-IRG1 axis” genes and “leptin and other obesity related genes” with CRC." (PMID 36430738, 2022). "Leptin reduces food intake and obesity is associated with increased leptin levels, through the induction of leptin resistance (Myers, Leibel, Seeley, & Schwartz, 2010)." (PMID 32624019, 2022). "In the present study, we assessed HOMA-IR, leptin, and adiponectin in lean and hypothyroid children and adolescents with obesity, and we also studied their association with thyroid hormone in such children." (PMID 35501770, 2022). "We further stratified the individuals into four groups to analyze the association between LEP polymorphisms and leptin levels with respect to sex and obesity status." (PMID 36293132, 2022). "The influence of genetic and epigenetic factors on leptin expression associated with obesity has been investigated." (PMID 35563103, 2022). "In men, both obesity and elevated BMI are associated with decreased testosterone levels, paralleled by elevated levels of estrogen, leptin and insulin, resulting in a state of hypogonadism." (PMID 36139133, 2022). "Altered leptin levels in obesity and anorexia have also been associated with leptin and leptin receptor gene polymorphism." (PMID 35886710, 2022). "High plasma leptin levels are correlated with body fat mass, with leptin resistance caused by decreased tissue sensitivity to prolonged high circulating leptin levels and increased susceptibility to obesity." (PMID 36235706, 2022). "Possible therapeutic routes that have been previously investigated involve the leptin pathway, due to its predisposition to cause obesity." (PMID 35328862, 2022). "The causes of obesity are very complex, and it is actually impossible to reliably determine the effect of a single factor, such as the presence of leptin in breast milk, on its prevention." (PMID 35684517, 2022). "The most-studied gene mutations contributing to obesity are mainly located in the leptin/melanocortin pathway which controls appetite and metabolism and regulates energy balance and homeostasis." (PMID 36613864, 2022). "In terms of obesity and obesity-related factors, MR analysis and other studies on the effects of adiponectin, leptin and TNF on EC risk have obtained different results." (PMID 35615721, 2022). "A few reports are available regarding the association between human leptin gene variants and obesity traits in India." (PMID 36619235, 2022). "Obesity has been largely associated with infertility, and leptin signalling is known to be dysregulated in the ovaries of obese females." (PMID 36855701, 2022). "Alongside infertility that is driven by leptin resistance, obesity is the major risk factor for polycystic ovary syndrome (PCOS)." (PMID 35239212, 2022). "The consequences of obesity or underweight are leptin resistance or leptin deficiency, respectively, which in both cases reduces leptin signaling in the brain." (PMID 35527735, 2022). "Adipokines, such as leptin and adipsin, are correlated with breast cancer progression, and as such, their expression levels are elevated in obesity-associated breast cancer." (PMID 35805056, 2022). "Several polymorphisms of both genes for leptin and leptin receptors have been studied in different populations for their potential association with obesity." (PMID 36551995, 2022).
Obesity (continued). "In fact, mice with a homozygous mutation for the leptin-producing gene ob (obese gene), were shown to develop both obesity and infertility." (PMID 36855701, 2022). "BPH/5 females have pre‐existing cardiometabolic risk before pregnancy (hyperphagia, obesity and leptin resistance, and hypoestrogenemia) and their phenotype is unique from BPH/5 males." (PMID 36065848, 2022). "Leptin deficiency leads to hyperphagia in mice, resulting in obesity and hyperglycemia at the age of 4–8 weeks." (PMID 35628192, 2022). "The top circulating biomarkers for archetype C were leptin and tyrosine, both associated with obesity and insulin resistance." (PMID 35106505, 2022). "A recent study also linked higher cord leptin levels with higher asthma risk at 3 years old in children born to mothers with obesity." (PMID 36189369, 2022). "We also observed an association with higher protein levels of the adipose-tissue-derived hormone leptin (q = 2.9 × 10−41), in line with the obesity association in this archetype." (PMID 35106505, 2022). "We designed this study to analyse the polymorphisms in human leptin gene and the association of sequence variants with obesity among the population in Kerala, South India." (PMID 36619235, 2022). "It is generally accepted that obesity is associated to high leptin and low adiponectin levels and inversely for undernutrition." (PMID 36010098, 2022). "Findings suggested a strong relationship between APOA2–265 T > C polymorphism and leptin and ghrelin levels as an effective possible mechanism for obesity which reported a high serum ghrelin among CC patients." (PMID 35883173, 2022). "This relationship is bidirectional as sleep deprivation can inhibit the production of the hormone leptin which regulates food intake and obesity is a risk factor for the development of obstructive sleep apnea." (PMID 35532192, 2022). "Having the correct mechanisms related to the action of leptin is a factor reducing the risk of obesity." (PMID 35684517, 2022). "Taken together, leptin affects Th2 cells indirectly by supporting the underlying Th1 inflammation in obesity." (PMID 35844529, 2022). "Mice with brain-specific PTP1B–/– deficiency showed resistance to diet-induced obesity and elevated insulin sensitivity via central modulation of leptin signal." (PMID 35607953, 2022). "The results demonstrated an interaction effect between sex and obesity within the LEP polymorphism and leptin level association in the dominant model of rs2167270 and rs7799039, particularly among obese women (interaction p = 0.04 and 0.02, respectively)." (PMID 36293132, 2022). "One DNAm loci of LEP methylation was associated with an early transient overweight trajectory and the other loci were associated with an early persistent obesity trajectory." (PMID 36397166, 2022). "There studies suggest that the relationship between post-natal leptin and later body weight is a U- shaped curve, and that deviation from normal leptin levels in either direction can increase obesity risk." (PMID 36619540, 2022). "In the same study, the gene variant of the leptin receptor, LEPR Q223, had demonstrated positive correlation with obesity risk, similar to the leptin gene (LEP −2548 AA)." (PMID 36551995, 2022). "The most severe obesity phenotype in humans and mice results from a deficiency of either the leptin or the leptin receptor." (PMID 34211092, 2021). "One of the key associates to obesity is the increase in leptin concentration in relation to fat mass." (PMID 34568497, 2021). "Multiple molecules and proteins are involved in the impairment of LepR signalling pathways, thus contributing to obesity-associated leptin resistance and hyperleptinaemia." (PMID 34208585, 2021). "Leptin is predominantly produced by adipocytes, and its serum levels increase significantly in obesity, which is associated with development of leptin resistance." (PMID 34201844, 2021).